LINC02210 (long independently transcribed non-coding RNA 2210)
Synonyms: FLJ25168; C17orf69; CRHR1-IT1
Gene: Long non-coding RNA gene on chromosome 17 (45,620,328 to 45,655,156, forward strand). Ensembl gene ENSG00000293460.
Diseases named in the same sentence as LINC02210 in open-access papers:
LINC02210 is named in the same sentence as 7 diseases in open-access papers, as found by Europe PMC text mining. Sharing a sentence is not in itself a finding about the gene and the disease. The quoted sentences say what the papers report.
Parkinson disease (2 papers, 2013 to 2025). A progressive degenerative disorder of the central nervous system characterized by loss of dopamine producing neurons in the substantia nigra and the presence of Lewy bodies in the substantia nigra and locus coeruleus. "Within the adult cortical analysis, KANSL1 and LINC02210 (chr17q21.31 cluster identified in the fetal analysis) were associated with eQTLs that were associated with brain-related traits (e.g., mood traits and Parkinson’s disease)." (PMID 40000109, 2025).
schizophrenia (2 papers, 2021 to 2025). A major psychotic disorder characterized by abnormalities in the perception or expression of reality. "Within the fetal analysis, genes located in chr17q21.31, such as MAPT-AS1, KANSL1, LINC02210, MAPK8P1P2, and RP11-259G18.1, were regulated by eQTLs that have known associations with cognition, schizophrenia, and alcohol consumption traits." (PMID 40000109, 2025).
autism (1 paper, 2023). Persistent deficits in social interaction and communication and interaction as well as a markedly restricted repertoire of activity and interest as well as repetitive patterns of behavior. "However, neither LINC02210 nor RP11−259G18.1 have previously been identified as causal autism genes." (PMID 37553252, 2023).
LINC02210 also shares sentences with these, for which no sentence is quoted: behavioral disorders (1 paper); celiac disease (1); ovarian carcinoma (1); progressive supranuclear palsy (1).